PRMT6 (protein arginine methyltransferase 6)
Diseases named in the same sentence as PRMT6 in open-access papers (continued):
Sharing a sentence is not in itself a finding about the gene and the disease.
cervical cancer (2 papers, 2022 to 2025). A primary or metastatic malignant neoplasm involving the cervix. "In HeLa cells, PRMT6 can also interact with p16 to methylate it and reduce the association of p16 and CDK4, suggesting that PRMT6 inhibits cell apoptosis through p16 arginine methylation, which also makes p16-associated gene therapy for cervical cancer a possible new strategy." (PMID 35311114, 2022). "In various cancer cell lines, including those of breast, lung, colorectal, and cervical cancers, PRMT6 has been found to inhibit the expression of cyclin-dependent kinase inhibitors (CKI) such as p21cip1/waf1, p27kip1, and p18ink4c, or to mitigate the association of p16ink4a with CDK4." (PMID 40461482, 2025).
colorectal cancer (2 papers, 2018 to 2023). A primary or metastatic malignant neoplasm that affects the colon or rectum. "In parallel with the discovery of the PRMT2/4 complex, another group identified PRMT5 and PRMT6 as functionally associating enzymes as oncogenic drivers in colorectal cancer." (PMID 37863263, 2023). "In the present study, we found that 23.7% of colorectal cancers showed positive staining of PRMT6 by immunohistochemistry and that the localization of the enzyme was exclusively nuclear." (PMID 29507670, 2018). "However, there is no clear evidence regarding the prognostic value of abnormal PRMT6 expression in colorectal cancer or the effect of PRMT6 regulation on CRC cells." (PMID 29507670, 2018).
lung adenocarcinoma (2 papers, 2021 to 2024). A carcinoma that arises from the lung and is characterized by the presence of malignant glandular epithelial cells. "PRMT6 levels are higher in the lung tissues of the patients with lung adenocarcinoma, which is associated with poor clinical outcomes." (PMID 34575100, 2021). "Depletion of PRMT6 activates the expression of p18 and inhibits the proliferation of lung adenocarcinoma cells." (PMID 34575100, 2021).
osteoporosis (2 papers, 2024 to 2025). A condition of reduced bone mass, with decreased cortical thickness and a decrease in the number and size of the trabeculae of cancellous bone (but normal chemical composition), resulting in increased fracture incidence. "Recent studies have demonstrated that PRMT6 has a regulatory role in glucose metabolism, and it has been shown that PRMT6 plays a key role in the progression of osteoporosis by promoting osteoclast formation and activation through the regulation of glycolysis." (PMID 41050704, 2025). "This dual approach of effective osteoclast inhibition without compromising osteoblast function underscores the therapeutic promise of PRMT6 targeting in the landscape of osteoporosis treatment." (PMID 39120025, 2024). "We found that inhibiting PRMT6 effectively mitigates bone loss in OVX mice, underscoring the potential of PRMT6 inhibitors in osteoporosis management." (PMID 39120025, 2024). "Given PRMT6's critical role in enhancing osteoclastogenesis both in vitro and in vivo, we investigated its potential as a therapeutic target for osteoporosis induced by OVX." (PMID 39120025, 2024). "This highlights PRMT6 as a promising therapeutic target for the treatment of osteoporosis." (PMID 39120025, 2024).
rhabdomyosarcoma (2 papers, 2021 to 2022). A rare aggressive malignant mesenchymal neoplasm arising from skeletal muscle. "Therefore, PRMT6 is expected to be a new therapeutic target for rhabdomyosarcoma." (PMID 35311114, 2022).
scrub typhus (2 papers, 2021 to 2023). Scrub typhus is a rare dust mite-borne infectious disease caused by the Orientia tsutsugamushi bacterium and characterized clinically by an eruptive fever which is potentially serious. "The top SNP related to susceptibility of scrub typhus was the rs11184708 SNP, which is located upstream of the protein arginine methyltransferase 6 (PRMT6) gene with a p = 6.447 × 10−13 value." (PMID 33807835, 2021). "Furthermore, the ILF2 and OAS genes were downstream of the top SNP, and the rs11184708 SNP located upstream of the PRMT6 gene, which is related to susceptibility to scrub typhus." (PMID 33807835, 2021).
spinobulbar muscular atrophy (2 papers, 2017 to 2023). "Furthermore, recent studies showed that the interaction of protein arginine methyltransferase 6 (PRMT6) with androgen receptor (AR) with poly-glutamine (Q) is significantly enhanced in an AR mutant associated with spinobulbar muscular atrophy (SBMA) leading to neurodegeneration." (PMID 28094300, 2017).
adenoma (1 paper, 2013). A neoplasm arising from the epithelium. "Quantitative analysis of microarray data confirmed that these methyltransferases, which included Setd3, Setd5, Suv39h2, Smyd3, Prmt3, Prmt6, Nsd1, and Nsd2 were up-regulated in metastases compared to adenomas, carcinomas, or disseminated cells." (PMID 23520493, 2013).
all (1 paper, 2023). "For rs56111229, the novel variant of the UKB all-cancer meta-analysis, our colocalization analysis also found that PRMT6 was one of the putative target genes." (PMID 37340002, 2023).
Autoimmunity (1 paper, 2023). The occurrence of an immune reaction against the organism's own cells or tissues. "FOXP3 is dimethylated by PRMT5 (or PRMT1, PRMT6) at R48 and R51, which attenuates the expression of immunosuppressive genes and may lead to autoimmunity." (PMID 37143582, 2023).
Azoospermia (1 paper, 2015). Absence of any measurable level of sperm,whereby spermatozoa cannot be observed even after centrifugation of the semen pellet. "Previous studies have demonstrated that PRMT6 interacts with AR and have suggested that Prmt6 is a non-obstructive azoospermia-susceptible locus." (PMID 26690413, 2015).
cardiac hypertrophy (1 paper, 2020). "Altogether, our results indicate that PRMT6 is a critical regulator of cardiac hypertrophy, implicating H3R2Me2a as an important histone modification." (PMID 32420474, 2020).
cervical tumor (1 paper, 2013). "When classified by health state, lung tumor and lymphoma tissue were reported to have zero transcripts per million (TPM) of PRMT6 transcripts, compared to 87 TPM for cervical tumor tissue and 58 TPM for kidney tumor tissue." (PMID 23800116, 2013).
colorectal tumors (1 paper, 2020). "Human colorectal tumors have lower levels of PPARA mRNA and protein than nontumor tissues and loss of PPAR-α promotes colon carcinogenesis by increasing DNMT1 methyltransferase mediated methylation of p21 and PRMT6 methyltransferase mediated methylation of p27." (PMID 32973493, 2020).
diabetic nephropathy (1 paper, 2025). "Conversely, reduced expression of protein arginine methyltransferase 6 (PRMT6) expression promotes lipid peroxidation and PL-PUFA synthesis by upregulating ACSL1, thereby exacerbating ferroptosis and accelerating diabetic nephropathy progression." (PMID 41288931, 2025).
endometriosis (1 paper, 2025). The growth of functional endometrial tissue in anatomic sites outside the uterine body. "Endometriosis-associated SNP-SNPinter models include 7 SNPs from 9 analyzed loci, such as rs17496332 (A > G) PRMT6, rs780093 (C > T) GCKR, rs10454142 (T > C) PPP1R21, rs3779195 (T > A) BAIAP2L1, rs440837 (A > G) ZBTB10, rs7910927 (G > T) JMJD1C, and rs8023580 (T > C) NR2F2." (PMID 41373783, 2025).
hypogonadism (1 paper, 2025). A disorder characterized by decreased function of the gonads. "In colocalization analyses, we find that several variants associated with testosterone levels and hypogonadism risk are located in or near genes related to liver function (UGT2B17, BRI3, PRMT6, PPIF)." (PMID 40316537, 2025). "In addition, we detected strong colocalization signals for PRMT6 and SHBG in the liver and adrenal gland that were linked to total testosterone and hypogonadism." (PMID 40316537, 2025).
insomnia (1 paper, 2025). A sleep disorder characterized by difficulty in falling asleep and/or remaining asleep. "Furthermore, clinical insomnia associations highlighted two loci that were primarily associated with RLS, MEIS1 consistent with earlier studies, and PRMT6, as well as five additional shared loci and one locus specific to clinical insomnia, PAX8 (PP = 0.8)." (PMID 41332830, 2025).
invasive breast carcinoma (1 paper, 2024). A carcinoma that infiltrates the breast parenchyma. "It is extremely interesting that the rs17496332 PRMT6 has been associated with the DNA methylation level (cg09367891 (chr1:107599246)) in invasive breast carcinoma." (PMID 38396861, 2024).
liver disease (1 paper, 2024). "Further studies are necessary to test the role of PRMT6 genetic polymorphisms in the susceptibility to liver disease (ALD and/or MetALD) and the role of estrogen, especially in premenopausal and postmenopausal female patients." (PMID 38704651, 2024). "Taken together, estrogen signaling protects mice from liver disease induced by a combination of alcohol and high-fat diet through upregulation of Prmt6 and suppression of integrin signaling." (PMID 38704651, 2024). "In this study, we examined the role of female sex hormones and arginine methyltransferase PRMT6 in liver disease development using a combination of high-fat diet (WD) feeding and alcohol in the drinking water." (PMID 38704651, 2024). "We found that female sex hormones protected mice from WD/alcohol-induced liver disease by promoting PRMT6 expression and suppressing integrin gene expression." (PMID 38704651, 2024). "We found that female sex hormones protected mice from WD/alcohol-induced liver disease by promoting PRMT6 expression, which prevented WD-induced weight gain and liver steatosis, and by suppressing integrin gene expression, which protected female mice from alcohol-induced liver fibrosis." (PMID 38704651, 2024).
liver fibrosis (1 paper, 2024). "We found that Prmt6 KO in WD-fed female mice promoted liver fibrosis, and alcohol feeding similarly promoted liver fibrosis in WT females." (PMID 38704651, 2024). "Estrogen treatment reduced liver fibrosis in males abolishing the difference between WT and Prmt6 KO." (PMID 38704651, 2024). "In male mice fed WD, Prmt6 KO resulted in a small increase in liver fibrosis similarly to female mice." (PMID 38704651, 2024). "We found that increased liver fibrosis in OVX Prmt6 KO mice fed alcohol correlated with elevated mRNA levels of Col1a1, Tgfb1, and Tnf, similarly to WT OVX mice." (PMID 38704651, 2024). "Thus, PRMT6 function in protecting female mice from alcohol-induced liver fibrosis is reduced, which correlates with observed minor differences in fibrosis levels between female wild type and Prmt6 knockout mice fed alcohol." (PMID 38704651, 2024). "We next examined the effect of OVX in Prmt6 KO mice on liver fibrosis by Sirius Red staining." (PMID 38704651, 2024). "Taken together, in WD-fed WT mice, OVX resulted in a small increase in liver fibrosis, which is likely due to PRMT6 loss (since the OVX effect is absent in KO WD-fed mice)." (PMID 38704651, 2024). "Using Prmt6 knockout mice, we confirmed that OVX-mediated weight gain, steatosis, and injury are PRMT6 dependent, while OVX-induced liver fibrosis is PRMT6 independent." (PMID 38704651, 2024). "Taken together, estrogen suppressed WD/alcohol-induced liver fibrosis development in both male and female mice independent of PRMT6." (PMID 38704651, 2024). "Similar results were observed in sham Prmt6 KO mice, which had liver fibrosis levels higher than WT WD controls, but no additional effect of alcohol was observed." (PMID 38704651, 2024). "However, in Prmt6 KO mice, alcohol did not produce additional increase in liver fibrosis." (PMID 38704651, 2024).
lymphoma (1 paper, 2013). A malignant (clonal) proliferation of B- lymphocytes or T- lymphocytes which involves the lymph nodes, bone marrow and/or extranodal sites. "Guided by the PRMT6 EST data, we therefore obtained human cell lines derived from lung tumor and lymphoma tissue." (PMID 23800116, 2013).
mood disturbance (1 paper, 2025). "The minor C allele of rs12028323, located at the PRMT6 (ENSG00000198890) and NTNG1 (ENSG00000162631) intergenic region, was associated with mood disturbance." (PMID 40440257, 2025).
neuroblastoma (1 paper, 2022). Neuroblastoma (NB) is the most common solid, extracranial childhood tumor.
prostate (1 paper, 2016). "Herein we aimed to uncover the potential oncogenic role of PRMT6 in prostate carcinogenesis." (PMID 27323813, 2016).
pulmonary fibrosis (1 paper, 2012). Chronic progressive interstitial lung disorder characterized by the replacement of the lung tissue by connective tissue, leading to progressive dyspnea, respiratory failure, or right heart failure. "Taking into consideration that TSP-1 is a major activator of TGF-β1, a cytokine involved in the pathogenesis of pulmonary fibrosis, it is conceivable that altered PRMT6 expression might be an important factor in regulating the fibrotic processes." (PMID 23202904, 2012). "How PRMT6 may contribute to the development of pulmonary fibrosis can currently only be speculated, however, it has previously been reported that PRMT6 may regulate expression of genes, either by modulation of histone 3 function or by interaction with specific gene promoter regions." (PMID 23202904, 2012).
steatosis (1 paper, 2024). Increased lipid within the cytoplasm of cells. "It is likely, however, that the weight gain effect reported here could be mediated by extrahepatic PRMT6, and the effect on liver steatosis could be due to PRMT6 expression in hepatocytes." (PMID 38704651, 2024).
cancer (43 papers, 2011 to 2025). A tumor composed of atypical neoplastic, often pleomorphic cells that invade other tissues. "Encouragingly, the outcomes of wound healing, Transwell, and colony formation assays were congruent, establishing that PRMT6 loss effectively inhibited cancer cell migration, invasion, and colony formation." (PMID 37813837, 2023). "Our all-cancer meta-analysis within UKB detected an association within the PRMT6 region." (PMID 37340002, 2023). "In addition, the dysregulation of PRMT6 is also associated with viral diseases, cancer and cardiac dystrophy." (PMID 35311114, 2022). "Taken together, p21 translocation promoted by PRMT6-mediated methylation appears to reduce chemosensitivity, which may cause chemoresistance of cancer cells." (PMID 26436589, 2015). "Interestingly, increased expression of PRMT6 is associated with a number of cancers." (PMID 34001852, 2021). "PRMT6 plays different roles in various cancers by influencing cell growth, migration, invasion, apoptosis, and drug resistance." (PMID 40164592, 2025). "PRMT6 is aberrantly overexpressed in multiple human cancers—including lung, liver, colon, gastric, endometrial, and prostate cancer—and its dysregulation is associated with aberrant methylation patterns and poor clinical prognosis." (PMID 41154773, 2025). "The type I PRMT family includes PRMT1, PRMT2, PRMT3, PRMT4, PRMT6, and PRMT8, which have been linked to various aspects of cancer development, including carcinogenesis, metastasis, and drug resistance." (PMID 39699269, 2025). "Many studies have reported on the role of PRMT6 in various cancers, where its expression is significantly increased in most tumors, indicating its crucial role in tumorigenesis." (PMID 38637831, 2024). "We believe that this finding would be important to improve the drug discovery and trial design for new anti-cancer drugs like PRMT6 inhibitor and other chemotherapeutics activating ferroptosis." (PMID 38994016, 2024). "The results compellingly demonstrated that PRMT6 knock-out significantly curtailed cancer cell metastasis, leading to a prolongation in the overall survival time of mice." (PMID 37813837, 2023). "Encouragingly, the introduction of PRMT6 led to a discernible enhancement in cancer cell metastatic potential." (PMID 37813837, 2023). "In light of this challenge, our investigation into the interaction of PRMT6 with JAK2 to activate the STAT3 pathway led us to consider PRMT6 inhibitors as a potentially effective approach for cancer treatment." (PMID 37813837, 2023). "To explore the role of PRMT6 in the promotion of breast tumorigenesis, we evaluated PRMT6 expression using RNA sequencing (RNA‐seq) datasets from The Cancer Genome Atlas (TCGA) and Gene Expression Omnibus (GEO)." (PMID 36941223, 2023). "Now, it is widely reported that PRMT6 acts as a tumor mediator and exerts a dual role in human cancer." (PMID 36792756, 2023). "To investigate this, we probed the interaction between STAT3 and JAK2 in cancer cells expressing either Vector or PRMT6." (PMID 37813837, 2023). "Colony formation assays were also conducted to quantify the colony-forming potential of cancer cells stably expressing Vector + sgRNA-Control, PRMT6 + sgRNA-Control, and PRMT6 + sgRNA-STAT3." (PMID 37813837, 2023). "The results notably revealed a significant upregulation of PRMT6 not only in BRCA tissues but also across various other cancer types." (PMID 37813837, 2023). "The study of PRMT6 inhibitors has been increasing to explore their efficacy as potential cancer therapy for various cancers." (PMID 37340002, 2023). "This modification proved indispensable for STAT3’s membrane localization, its interaction with JAK2, STAT3 Y705 phosphorylation, and PRMT6-driven cancer cell metastasis." (PMID 37813837, 2023). "At the same time, we highlight the role of PRMT6 in different cancers, including the differentiation of its promotive or inhibitory effects and the underlying mechanisms." (PMID 35311114, 2022).